CD4 (CD4 molecule)
Diseases named in the same sentence as CD4 in open-access papers (continued):
Sharing a sentence is not in itself a finding about the gene and the disease.
Autoimmunity (continued). "Investigators observed that anti-cancer efficacy without concomitant autoimmunity was due to lineage-specific induction of CD8+ T-cell responses to GUCY2C, without CD4+ helper T-cell or antibody responses." (PMID 28914772, 2017). "Again, we did not observe any modification in the capacity of T cells to mediate autoimmunity that could have been caused by the lack of S100A4 expression and mice adoptively transferred with S100a4Gfp/Gfp CD4+ T cells developed EAE to the same extent as those receiving S100a4+/+ CD4+ T cells." (PMID 26734465, 2015). "Fixing the TCR delays the onset of autoimmunity in the TGF-βRIIf/f CD4-cre mice; however, activated CD44hi CD4 T cells do emerge over time (data not shown)." (PMID 25569154, 2015). "Different than the patients with autoimmunity, there was no change in the frequency of the CD8 to CD4 ratio within the CD161hi T cells." (PMID 21915328, 2011). "Similar to the immune phenotype observed in the CD4-DNTGFβRII mice, several other mouse strains (non-obese diabetic, MRLlpr/lpr, CD25KO, TGF-β1KO) develop autoimmunity with aging." (PMID 22194977, 2011). "Transgenic expression of the IL2Rβ chain in IL2Rβ chain (-/-) thymocytes corrects the lack of CD4+CD25+ peripheral T cells in IL2Rβ chain (-/-) mice and prevents lethal autoimmunity." (PMID 15606917, 2004). "Recent single-cell RNA-sequencing revealed that EBV-infected B cells in SLE are transcriptionally distinct, with enhanced EBNA2-driven antigen presentation and ability to activate autoreactive CD4+ T cells, which positions EBV as an active driver rather than a passive trigger of autoimmunity." (PMID 42311676, 2026). "However, unlike in Sin3a−/−FoxP3cre, the percentages and numbers of CD4+ and CD8+ T cells in the SLOs of Sin3a−/−CD4cre mice were greatly reduced, providing an explanation as to why these mice do not develop fatal autoimmunity." (PMID 39156895, 2024). "The %TSDR/CD4 was raised in individuals with IPEX compared to healthy controls, individuals with non-autoimmune monogenic neonatal diabetes, and non-IPEX monogenic autoimmunity with overlapping phenotype." (PMID 36600150, 2023). "In conclusion, our study provides strong evidence that blocking of the PD1/PDL-1 pathway is a promising effective immunotherapeutic strategy against VL that restores protective antigen-specific CD4+ and CD8+ type 1 responses without inducing autoimmunity or immunopathology." (PMID 29610255, 2018). "With the demonstration of both prophylactic and therapeutic efficacy of GUCY2C vaccines, and no observable autoimmunity, the Ad5-GUCY2C-S1 vaccine was developed for clinical use, replacing the CD4+ helper T-cell epitope with a universal human CD4+ T-cell epitope, known as PADRE." (PMID 28914772, 2017). "However, in addition to B cells, CD4 and CD8 T cells as well as myeloid cells were upregulated in miR-146a−/− mice, and this finding indicates that these cells also likely contribute to the observed autoimmunity and renal phenotype, which might or might not be a consequence of dysregulated Bregs." (PMID 31666653, 2019).
colitis (1,090 papers, 2005 to 2026). Inflammation of the colon. "On the other hand, global loss of ERβ in a mouse model of colitis led to decreased levels of Treg cells and increased severity of disease, suggesting an opposite effect in CD4+ T cells from ERα in Tregs." (PMID 41580387, 2026). "Rag1−/− mice receiving CD4+ CD45Rbhi T cells alone developed severe colitis, as evidenced by increased weight loss, higher pathological scores, and intestinal TNF‐α and IL‐6 levels, which were inhibited by co‐transfer of WT or miR‐10a‐deficient Tregs." (PMID 41178490, 2026). "The results showed that CD4+CD25+ Treg from both groups equally suppressed disease progression in adoptive transfer colitis models, as evidenced by similarly reduced weight loss and ameliorated colonic lesions." (PMID 40757098, 2025). "T cell–selective PRDM1 deletion in mice caused early-onset colitis because of excessive CD4+ T cell proliferation, suggesting a major contribution for BLIMP-1 on Treg homeostasis and function." (PMID 40773294, 2025). "TRPV1 is abundantly expressed in immune cells, including resident colonic immune cells, particularly CD4+T cells, and has been implicated in the underlying pathogenesis of T cell-mediated murine colitis." (PMID 40560060, 2025). "As such, CD4+ CD45RBhigh cells, Th1, Th17, and IL-10-deficient CD4+ T cells were transferred into immunodeficient mice to induce colitis." (PMID 40649879, 2025). "Increased expression of PDK4 has been associated with colitis, with its substrate accumulating in CD4+ T cells of patients with inflammatory bowel disease." (PMID 40375928, 2025). "The regulatory role of PANK4 in CD4+ T-cell proliferation was confirmed in models of experimental colitis and influenza A virus infection, where Pank4-deficient CD4+ T cells exhibited greater expansion than their wild-type counterparts when co-transferred." (PMID 40962808, 2025). "At 16W, the percentage of CD4+ T cells in the spleens of colitis-associated CRC mice in the Combo group was significantly higher than in the NS group." (PMID 39840995, 2025). "Rag2-/- hosts that received Cars2+/- versus WT CD4+ T cells exhibited severer body weight loss and histological colitis." (PMID 40303402, 2025). "Increased IL-10 production by Rorγt-deficient CD4 T cells has been seen in a colitis model in which reduced Blimp-1 expression contributed to this phenotype, but we found similar low levels of Blimp-1 expression by DKO and TKO cells at this timepoint." (PMID 40819821, 2025). "Paradoxically, while CD4+ T cell‐specific Atg7 deficiency exacerbated colitis, ATG7 expression was upregulated in active IBD patients." (PMID 40887825, 2025). "Changes in CD4+ T cell infiltration into tissues has been associated with various chronic inflammatory disorders, including colitis, HIV and cancer." (PMID 40265075, 2025). "In the adoptive T-cell transfer model of colitis, transfer of naive CD4+CD45RBhigh T cells into HVEM-deficient recipient mice results in accelerated and lethal intestinal inflammation, underscoring a dominant protective role for HVEM expressed on host cells." (PMID 41030453, 2025). "Published data suggest that UHRF1 is dispensable for iTreg generation, yet others have reported that iTreg generation from UHRF1-deficient CD4+ Tconv cells augments their suppressive function in a colitis model of inflammation." (PMID 40956625, 2025). "In contrast, other studies demonstrate that iTregs generated from UHRF1-deficient CD4+ T cells exhibit hypersuppressive function when adoptively transferred into lymphocyte-deficient mice with Tconv cell–mediated colitis." (PMID 40956625, 2025). "This consequent reduction of CD4+ T cells in colitis tissue is postulated to heighten the risk of colitis-associated colorectal cancer." (PMID 38607733, 2024). "NCOR1-deficient Treg cells failed to protect mice from severe weight loss and intestinal inflammation associated with CD4+ T cell transfer colitis, indicating impaired suppressive function." (PMID 39466314, 2024).
colitis (continued). "Th17 and Treg cells, subsets of CD4+T cells, have been recently identified as immune cells closely associated with colitis." (PMID 38397562, 2024). "Experiments have shown that colitis prompts a migration of gut-microbe-responsive CD4+ T cells to skin-associated lymph nodes, increasing skin neutrophils and decreasing Tregs specific to skin microbes, all of which contribute to skin inflammation." (PMID 38654394, 2024). "Here, we found that GzmbB-deficient CD4+ T cells induced more severe colitis in Rag1-/- mice than wild-type (WT) CD4+ T cells." (PMID 38841892, 2024). "We isolated lymphocytes from the livers of these mice and found increased frequencies of Foxp3+ Treg in Mdr2-deficient mice upon acute DSS colitis induction and comparable frequencies of IFNγ+ and IL-17A+ CD4+ T cells." (PMID 38510236, 2024). "Butyrate-treated GzmB-deficient CD4+ T cells demonstrated more severe colitis compared to butyrate-treated WT CD4+ T cells in the T cell transfer model." (PMID 38841892, 2024). "We identified the subnetwork of master gene regulators responsive for the observed changes in gene expression associated with colitis in colonic CD4+ T cells." (PMID 38719901, 2024). "Protection from colitis in IL-10cKO mice was associated with an expanded population of IL-10–producing type 1 Tregs (Tr1, CD4+Foxp3−) in the colonic lamina propria that produced more IL-10 on a per-cell basis compared with wild-type intestinal Tr1 cells." (PMID 37314833, 2023). "All the mice receiving the naive CD4+ T cells developed colitis, as indicated by the substantial loss of body weight, histologically evident damage, and a reduction in colon size." (PMID 37875468, 2023). "Genetic deletion of RELMα obviously alleviates infection-induced colitis in mice and shows the deficiency of IL-23p19 in macrophages as well as the decrease of IL-17A in CD4+ T cells." (PMID 36691020, 2023). "Consistent with the results from DSS-induced colitis, exposure to CR infection also caused an increase in TCRγδ+CD8αα+ IELs but a decrease in TCRαβ+CD4+·IELs in the colon of Cd177−/− mice compared with WT controls." (PMID 36729914, 2023). "Undoubtedly, CD4-specific Tfam KO mice are more susceptible to chemical-induced experimental colitis model using 3% DSS." (PMID 37809060, 2023). "To determine the cause of lethal colitis in Rag1KOTslprKO mice, we characterized the adoptively transferred CD4+ T cells in the recipient animals." (PMID 37427591, 2023). "Reduced AICD has also been observed for TNFR2-deficient CD4+ T cells and seem to result in enhanced CD4+ T cell transfer-induced colitis." (PMID 38020877, 2023). "G protein-coupled receptor 120 (GPR) is implicated in regulating CD4+ T cell production of IL-10 in the gut to inhibit the development of colitis, which identifies GPR 120 as a potential therapeutic target." (PMID 38137450, 2023). "Considering that the colonic microbiome is a major regulator of innate and adaptive immune response in the colon, we investigated its role in lethal colitis caused by incoming CD4+ T cells in Rag1KOTslprKO mice." (PMID 37427591, 2023). "Previous studies have revealed that transferring naive CD4+ T cells into Treg-deficient mice led to colitis, while Treg transfer into colitis rodents significantly relieved intestinal inflammation." (PMID 37968625, 2023). "Although TSLP does not affect thymic Treg differentiation, TSLP receptor-deficient induced Treg cells derived from naïve CD4+ T cells are less activated in an adoptive transfer model of colitis." (PMID 36717741, 2023). "We previously observed that RA synthesis inhibition via WIN 18,446 treatment decreased the expression of α4β7 in activated CD4+ T cells; this was associated with decreased colitis and increased survival in Smad3−/− mice." (PMID 37764666, 2023). "Scid mice started to develop clinical signs of colitis, including weight loss with loose stool and/or diarrhea, three weeks after the adoptive transfer of CD4+CD45RBhi T cells." (PMID 38012544, 2023).
colitis (continued). "Systemic CDK9 inhibition led to histological improvement of immune-mediated colitis and was associated with targeted suppression of colonic CD4+ T cell-derived IFN-γ and IL-17A." (PMID 35660024, 2022). "TIGIT deficiency protects mice from DSS-induced colitis by reducing IL-17A–producing CD69+CD103− CD4+ TRM cells." (PMID 35844584, 2022). "An increased accessibility of Il21 promoter is observed in CKO CD4+ T cells, and severity of Blimp-1 deficiency–mediated colitis can be restored by histone acetyltransferase CBP/p300 inhibitor." (PMID 35503415, 2022). "In mouse model, naïve CD4 T-cells transferred into the lymphopenic Recombination Activating gene 1 Knock-out (Rag-KO) mice massively proliferated and caused colitis in the transferred mice." (PMID 35633761, 2022). "Lysophosphatidylserine-induced aggravation of colitis is prevented by P2y10 deficiency in CD4+ T cells, demonstrating that dysbiotic microbiota-derived LysoPS exacerbates colitis by modulating Th1 cell metabolism." (PMID 35608941, 2022). "CD4+ T cell depletion effectively reduced symptoms of colitis as well as colonic expression of Th17 and Th1 cytokines in mPGES-1−/− mice, suggesting the requirement of CD4+ T cells in the exacerbation of DSS-induced colitis under mPGES-1 deficiency." (PMID 34983695, 2022). "Different from the proinflammatory responses of CerS2 knockout in CD4+ T cells, transfer of CerS6-deficient CD4+ T cells induced less colitis compared to WT cells." (PMID 36052066, 2022). "Butyrate enhanced histone H3 acetylation in the promoter, and conserved non-coding sequence regions of the Foxp3 locus, induced the differentiation of Treg cells in the colon, and also improved the colitis caused by CD4 (+) T cells in mice." (PMID 36189293, 2022). "In conclusion, our results demonstrate that the upregulation of pathogenic Foxp3-CD25+CD4+ T cells induced by proinflammatory DCs is closely linked with increased susceptibility to DSS-induced colitis in iNKT cell-deficient Yeti/CD1d KO mice." (PMID 36499642, 2022). "Coadministration of P2ry10−/yP2ry10b−/y Treg cells also prevented LysoPS-mediated aggravation of colitis, as evidenced by decreases in body weight loss and histopathological score, in Rag2−/− mice that received naive CD4+ T cells." (PMID 35608941, 2022). "Systemic CDK9 inhibition resulted in an improved colitis score associated with diminished Th1 and Th17 cytokine production by colonic CD4+ T cells." (PMID 35660024, 2022). "Collectively, the composition of the Blastocystis-associated CD4 compartments in colonic LP from the DSS-induced colitis model indicated this organism's direct interaction with the host’s adaptive immune system." (PMID 35435504, 2022). "Discriminatory markers of colitis risk related primarily to T cells, especially the frequency of CD4+ T cells (AUC = 0.652)." (PMID 36248910, 2022). "Using a T cell transfer model of colitis this group demonstrated the IBD microbiome caused more severe CD4+ T cell-mediated colitis, compared to healthy microbiome." (PMID 36713364, 2022). "We observed lower Gpr174 expression in colonic Treg cells, and P2ry10 and P2ry10b deficiency in CD4+ T cells prevents LysoPS-dependent colitis exacerbation." (PMID 35608941, 2022). "Our results demonstrate that increases in the prevalence of Foxp3−CD25+CD4+ pathogenic effector T cells correlate with increased susceptibility to DSS-induced colitis in Yeti/CD1d KO mice." (PMID 36499642, 2022). "Meanwhile, in line with our studies that specific deletion of Mettl14 in CD4+ T cells has also been shown to cause spontaneous colitis in mice, which is the outcome of T cell dysfunction and subsequent loss of the inhibitory activity of Treg cells." (PMID 36341394, 2022). "Collectively, our studies uncover a previously unappreciated pathogenic role of a subset of IFN-γ-producing cytotoxic CD4+ T cells in IL-23-driven colitis." (PMID 35468944, 2022).
colitis (continued). "Adoptive transfer of the G-protein Galphai2-deficient CD4+T-cells induced spontaneous colitis in mice." (PMID 35163775, 2022). "Together, these results indicated that the increased expression of proinflammatory genes, the accumulation of colitogenic CD4+ T cells, and the development of severe colitis in TAGAP-deficient mice is dependent on the microbiota." (PMID 36704549, 2022). "A population of CD4+IL-17F+ T cells was sufficient to induce colitis in RAG1-deficient recipients, where the transition of these precursors to Th1-like cells was an absolute requirement for disease." (PMID 36012618, 2022). "After adoptively transferring naïve CD4+ T cells from syngeneic mice to recombinase activating gene-2-deficient (Rag2-/-) mice, the mice showing the colitis symptom in the form of loose stool in 4-6 weeks were randomly divided into two groups." (PMID 35990633, 2022). "Of note, similar observations have been made for IL-22-producing CD4+ T cells in colitis-associated colon cancer." (PMID 34566952, 2021). "The relative low number of total T cells containing a mixture of naïve/memory and CD4/CD8 T cells were transferred into recipient mice which were insufficient to cause colitis in B6 Rag1-/- recipients." (PMID 34950143, 2021). "We finally established a classic of T-cell mediated model colitis in Rag1-deficeint mice, in which a mixture of CD4+CD45RB+CD25- effector T cells plus WT or PDK1-deficient Treg cells was transferred." (PMID 34646383, 2021). "Attenuation of disease in an experimental model of transfer colitis when Hobit- and Blimp-1-deficient CD4+ T cells were transferred, confirmed the disease-driving role of CD4+ TRMs in IBD." (PMID 34113356, 2021). "The second model was adoptive transfer colitis induced by transfer of CD4+CD25−CD62L+ T lymphocytes into immunodeficient mice causing TH17-mediated mucosal inflammation and reactive epithelial proliferation." (PMID 34867313, 2021). "The deficiency in CD4+CD25+ regulatory cells is important for lymphopenic SCID mice to develop colitis after transfer with naive CD45RBhi T cells." (PMID 33923792, 2021). "Preclinical studies also have demonstrated that the therapeutic effect of MenSCs on the course of experimental murine colitis is associated with significantly higher level of CD4+CD25+FOXP3+ Treg cells." (PMID 33554005, 2021). "For instance, SCFAs can aggravate colitis-associated inflammation in mice by inducing expression of T-bet and IFNγ in Tregs and in conventional CD4+ T cells." (PMID 33397404, 2021). "DSS-induced colitis was associated with increased percentages of Foxp3+CD4+Treg cells in cLP in both WT mice and Lgals1−/− mice with respect to their control non-inflamed counterparts." (PMID 34262567, 2021). "Taken together, Tec-deficient naïve CD4+ T cells differentiated markedly more towards effector Th17 cells with enhanced plasticity towards Th1/exTh17 cells during overt colitis with pronounced inflammatory phenotype." (PMID 35003062, 2021). "These transferred naïve CD4+ T cells develop into Th1 and Th17 effector cells by exposure to gut microbiota antigens and cause severe colitis which recapitulates major aspects of human IBD." (PMID 35003062, 2021). "Our own studies have demonstrated that CD4+ T cells and B cells deficient in the IL-4/IL-13 common receptor IL-4Rα are protected from oxazolone-induced colitis." (PMID 32410852, 2020). "Overexpression of T-bet in CD4+ T cells exacerbated experimental colitis, whereas Tbx21-deficient CD4+ T cells were unable to modulate the development of colitis." (PMID 32369982, 2020). "In other studies, a highly pathogenic subset of stem-like CD4 T cells was identified in a mouse model of colitis." (PMID 33166339, 2020). "In vivo, effector functions were compromised since adoptive transfer of NCOR1-deficient CD4+ T cells resulted in attenuated colitis due to lower frequencies of IFNγ+ and IFNγ+IL-17A+ Th cells and overall reduced CD4+ T cell numbers." (PMID 32318068, 2020).